PPARG (peroxisome proliferator activated receptor gamma)
Diseases named in the same sentence as PPARG in open-access papers (continued):
Sharing a sentence is not in itself a finding about the gene and the disease.
metastatic prostate carcinoma (3 papers, 2013 to 2023). A carcinoma that arises from the prostate gland and has spread to other anatomic sites. "PPARγ promoted metastatic prostate cancer through activation of lipid signaling pathways." (PMID 36835200, 2023). "PPARG is a classic transcription factor triggered by ligand, activating lipid signaling by upregulating acetyl-CoA carboxylase (ACC), fatty acid synthase (FASN) and ATP citrate lyase (ACLY), and promotes the metastatic prostate cancer." (PMID 37932808, 2023).
morbid obesity (3 papers, 2018 to 2022). An excess of body weight, normally defined as an individual with a body mass index greater than 35 or a body weight greater than one hundred percent of ideal body weight. "Rarer nsSNPs such as the peroxisome proliferator-activated receptor gamma (PPARG) rs1800571 with gain-of-function mutation (Pro115Gln) has also been found to be possibly pathogenic for morbid obesity." (PMID 29755414, 2018). "We also found that both miR-19a and miR-19b increased their expression at the same time as the PPARG mRNA expression levels decreased in the abdominal subcutaneous adipose tissue (aSAT) of patients with morbid obesity, trends that are reversed after weight loss induced by bariatric surgery (BS)." (PMID 36555437, 2022). "In view of the results obtained in vitro, we sought to verify whether the expression levels of the miR-19 family and PPARG are deregulated in the adipose tissue in morbid obesity, and we found that they present opposite profiles." (PMID 36555437, 2022). "Taking into account the previous results, we decided to verify whether the miR-19 family and PPARG gene expression are deregulated in morbid obesity." (PMID 36555437, 2022).
mycobacterial infection (3 papers, 2012 to 2023). "Current evidence indicates that mycobacterial infection causes a time-dependent increase in PPARγ expression through mechanisms that involve pattern recognition receptor activation." (PMID 22851964, 2012). "PPARγ is regulated and active in lipid droplet-enriched cells, and PPARγ may regulate processes associated with lipid-droplet formation in leukocytes during intracellular mycobacterial infection." (PMID 22851964, 2012). "It has been demonstrated that PPARγ activation by mycobacterial infection has a key role in LDs biogenesis." (PMID 36909724, 2023). "The formation of LDs in host cells during mycobacterial infections is a frequent phenomenon, which happens in a mechanism highly regulated by cellular receptors, such as TLRs, scavenger receptors, and PPARγ." (PMID 36909724, 2023). "Here, we will review the molecular mechanisms that regulate PPARγ expression and function during mycobacterial infection." (PMID 22851964, 2012). "Although the significance of peroxisome proliferator-activated receptor gamma (PPARγ) activation by mycobacteria is not fully understood, recent findings are beginning to uncover a critical role for PPARγ during mycobacterial infection." (PMID 22851964, 2012). "Together, accumulating data on PPARγ-dependent effects on immune response during mycobacterial infection suggest that PPARγ induction is advantageous for this host-adapted intracellular pathogen within the lung microenvironment." (PMID 22851964, 2012). "Specifically, we discuss the host response to Mycobacterium infection related to the regulation of PPARγ expression by mycobacteria and PPARγ-dependent effects on mycobacterial-induced modulation of host cell lipid metabolism and immune responses." (PMID 22851964, 2012). "The mechanisms involved in PPARγ-induced lipid droplet biogenesis in mycobacterial infection are still not completely understood." (PMID 22851964, 2012). "Recent studies have demonstrated that mycobacterial infection significantly increases PPARγ expression in human and mouse macrophages with important consequences for immune and metabolic host responses to infection." (PMID 22851964, 2012). "The function of PPARγ activation in the immune response to mycobacterial infection was investigated." (PMID 22851964, 2012). "Increased PPARγ expression during mycobacterial infection is important for lipid metabolism and inflammatory responses of macrophages." (PMID 22851964, 2012). "Notably, PPARγ expression is highly upregulated during mycobacterial infection." (PMID 22851964, 2012). "In addition, treatment with the fatty acid synthase inhibitor C75, a PPARγ target, has been shown to inhibit significantly lipid droplet formation induced by mycobacterial infection with or without apoptotic cells, confirming the role of new lipid synthesis in lipid droplet biogenesis." (PMID 22851964, 2012).
myxoid liposarcoma (3 papers, 2012 to 2022). A liposarcoma characterized by the presence of round non-lipogenic primitive mesenchymal cells and small signet ring lipoblasts within a myxoid stoma with a branching vascular pattern. "We analyzed PPARγ expression using immunohistochemistry (IHC) in 46 patients with myxoid liposarcoma [MLS; median age, 47 years (range, 14–90 years) and mean follow-up period, 91 months (range, 13–358 months)]." (PMID 27401457, 2016). "The phenomenon of adipocytic maturation is comparable to myxoid liposarcomas in patients treated with trabectedin and the thioglitazone family of PPARγ agonists." (PMID 23272660, 2012). "In addition, PPARγ agonists, thioglitazones, have been reported to produce similar histological effects in myxoid liposarcomas." (PMID 23272660, 2012).
Nasal polyps (3 papers, 2005 to 2025). "Nasal polyps exhibited lower levels of PPARα and PPARγ than normal nasal mucosa and these levels were, for PPARγ, further reduced following steroid treatment." (PMID 16271155, 2005). "Nasal polyps exhibited lower mRNA expression levels of PPARα and PPARγ than normal nasal mucosa and these levels were, for PPARγ, further reduced following four weeks of treatment with local steroids." (PMID 16271155, 2005). "The RT-PCR analysis of total RNA extracted from nasal biopsies and nasal polyps demonstrated the presence of PPARα, PPARβδ, PPARγ and β-actin in all samples." (PMID 16271155, 2005). "Nasal polyposis represents a chronic type of inflammation and the lower levels of PPARγ in comparison with normal nasal mucosa might reflect a reduced ability of the diseased mucosa to respond to airway inflammation, thereby facilitating the polyp formation." (PMID 16271155, 2005). "Thus, the beneficial effect of glucocorticoid treatment on nasal polyposis may adversely affect the down-regulation of PPARγ." (PMID 16271155, 2005). "The down-regulation of PPARγ, in nasal polyposis but not in turbinates during symptomatic seasonal rhinitis, suggests that PPARγ might be of importance in long standing inflammations." (PMID 16271155, 2005).
nasopharyngeal carcinoma (3 papers, 2019 to 2025). A carcinoma arising from the nasopharyngeal epithelium. "RGZ inhibits PPARG and AMPK signaling in human nasopharyngeal cancer cells." (PMID 36114448, 2022).
premature ovarian failure (3 papers, 2019 to 2024). "Additionally, PPARγ, a potential therapeutic target, has also rescued its expression by treating the premature ovarian failure mice with Esculentoside A. Our results advocated that Esculentoside A could restore folliculogenesis in premature ovarian failure mice." (PMID 32759462, 2020). "Among these miRNAs, miR‐202 is gonad‐specific and might be important in the prevention of premature ovarian failure (POF), and miR‐27b and its target, peroxisome proliferator activated receptor gamma (PPARγ), is crucial for the maturation of porcine oocytes." (PMID 30151880, 2019).
respiratory infections (3 papers, 2021 to 2024). "Beyond the pathogenesis of stable COPD, the role of PPARγ agonists in COPD exacerbation, which is most frequently caused by respiratory infections, has been suggested." (PMID 34021254, 2021).
retinal degeneration (3 papers, 2014 to 2024). Degeneration of the retina. "Our study linked TREM2 signaling with PPARγ activation, and provided a potential therapeutic target for the management of retinal degeneration." (PMID 39187498, 2024). "Administration of GW9662 caused exacerbated photoreceptor cell death and ONL thinning, further supporting that PPARγ signaling in microglial cells mediated the protective effect of microglia during retinal degeneration." (PMID 39187498, 2024). "Out study identified PPARγ as an important mediator of TREM2 activation in microglial cells during retinal degeneration." (PMID 39187498, 2024). "Collectively, these results suggested that PPARγ signaling confers the protective role of microglial cells during retinal degeneration." (PMID 39187498, 2024). "Our findings suggested that the protective effect of microglia during retinal degeneration was dependent on Trem2 expression and carried out via the activation of PPARγ and the consequent upregulation of CD36 expression." (PMID 39187498, 2024). "Taken together, our study underscored the importance of TREM2 in regulating microglia activation, and identified PPARγ signaling and CD36 as potential mechanisms and effector molecules of TREM2 in the context of retinal degeneration." (PMID 39187498, 2024). "Our data suggest that αB crystallin plays a critical role in protection of NaIO3-induced oxidative stress and retinal degeneration in part through upregulation of AKT phosphorylation and PPARγ expression." (PMID 24874187, 2014). "Further, our studies also suggest that αB crystallin plays a critical role in protection of NaIO3-induced oxidative stress and retinal degeneration in part through upregulation of AKT phosphorylation and PPARγ expression." (PMID 24874187, 2014). "In conclusion, our data show that αB crystallin plays a critical role in protection of NaIO3 induced oxidative and retinal degeneration in part through upregulation of AKT phosphorylation and PPARγ expression." (PMID 24874187, 2014).
retinal ischemia (3 papers, 2019 to 2022). A ischemic disease that involves the retina. "Besides, PPARγ also controls the NF-κB-dependent NLRP3 priming in different contexts including astrocytes and retinal ischemia/reperfusion." (PMID 33716981, 2021).
rotator cuff tear (3 papers, 2023 to 2025). "Studies using selective agonists of the RA receptor gamma in rotator cuff tear showed similar results for amelioration of fat deposition in muscle and reduced gene expression of Cebpα and Pparγ." (PMID 40846464, 2025). "PI3K‐AKT signalling promoted adipogenesis via suppression of the Gsk‐3β/β‐catenin axis and upregulation of Pparγ, in a mouse model of rotator cuff tear." (PMID 40846464, 2025).
Shock (3 papers, 2013 to 2026). The state in which profound and widespread reduction of effective tissue perfusion leads first to reversible, and then if prolonged, to irreversible cellular injury. "Angiotensin II, a vasopressor used in refractory septic shock, inhibits PPARG activity, thereby increasing blood pressure." (PMID 34573990, 2021).
Uterine leiomyoma (3 papers, 2015 to 2021). The presence of a leiomyoma of the uterus. "Taken together, metabolites of DEHP may be associated with estrogen-dependent diseases such as uterine leiomyoma that result from an increase in aromatase and estradiol levels attributable to dysregulation of PI3K signaling and PPARγ activity." (PMID 27983712, 2016). "Curcumin significantly inhibited proliferation in Eker rat-derived uterine leiomyoma cell lines (ELT-3) via activation of PPARγ, where curcumin acted as a PPARγ ligand and, in the presence of a PPARγ antagonist, the inhibitory effect of curcumin was reversed." (PMID 25665066, 2015).
abscess (2 papers, 2008 to 2015). An inflammatory process characterized by the accumulation of pus within a newly formed tissue cavity which is the result of a bacterial, fungal, or parasitic infection or the presence of a foreign body. "Additionally, the edge of the abscess areas showed enhanced PPARγ activity, demonstrating the contribution of PPARγ to this decreased bacterial burden." (PMID 26713087, 2015).
acute coronary syndrome (2 papers, 2009 to 2022). Signs and symptoms related to acute ischemia of the myocardium secondary to coronary artery disease. "Among men, homozygous carriers of the variant allele of PPARγ Pro12Ala were at higher risk of acute coronary syndrome than homozygous common allele carriers (hazard ratio (HR) = 2.12, 95% confidence interval (CI): 1.00–4.48)." (PMID 19500413, 2009). "HR for acute coronary syndrome subdivided by alcohol intake and PPARγ Pro12Ala genotype." (PMID 19500413, 2009).
alveolar proteinosis (2 papers, 2007 to 2022). "In alveolar proteinosis, PPARγ regulates the formation of FM by regulating the expression of ABCG1." (PMID 35432274, 2022).
anaplastic thyroid cancer (2 papers, 2009 to 2020). "Ligand activation of PPARγ induces growth inhibition and apoptosis in different thyroid cell lines, including anaplastic thyroid cancer cells." (PMID 32397091, 2020). "Activation of PPARγ could represent a novel treatment option for anaplastic thyroid cancer in order to extend life duration thus warranting a good quality of life." (PMID 32397091, 2020). "In contrast, Aiello and colleagues demonstrated a complete blunting of the antiproliferative effect of TZDs on a variety of responsive anaplastic thyroid cancer (ATC) cells when PPARγ expression was diminished by siRNA and TZD concentrations of 10 μM were used for 4 days." (PMID 19267912, 2009).
autoimmune myocarditis (2 papers, 2011 to 2016). Autoimmune myocarditis is an autoimmune disease that affects the heart. "Experimental autoimmune myocarditis is another model in which the potential involvement of PPARγ was investigated." (PMID 21382489, 2011).
autoimmune uveitis (2 papers, 2008 to 2009). An autoimmune form of uveitis (disease). "Furthermore, presented are explorations of the roles of PPARγ in microglial cell functions, therapeutic potentials of PPARγ ligands on ocular diseases such as AMD, diabetic retinopathy, autoimmune uveitis and optic neuritis, and the role of PPARγ in the breakdown of blood-retinal barrier." (PMID 19657396, 2009).
bone cancer (2 papers, 2021 to 2022). A primary or metastatic malignant neoplasm affecting the bone or articular cartilage. "This study is designed to determine the gene and protein expression pattern of PPARγ and its association with tumor severity, metastasis, recurrence in different types of primary bone tumors and bone normal tissues." (PMID 35922782, 2022). "This study is focused on illuminating the PPARγ gene and protein expression pattern, its association with tumor deterioration and its diagnostic value in different types of primary bone tumors." (PMID 35922782, 2022). "Our preliminary study was conducted using a relatively small sample size (due to the bone tumor incidence in our region); however further studies with more samples are suggested to confirm the diagnostic potential of PPARγ in bone tumors." (PMID 35922782, 2022). "In the current study, amongst malignant bone tumors, osteosarcoma tumors expressed a higher level of PPARγ gene and protein level compared to Ewing Sarcoma tumors." (PMID 35922782, 2022). "In conclusion, the PPARγ gene and protein revealed different expression patterns in primary bone tumors with a significantly elevated level of expression in malignant tumors with higher degrees of deterioration." (PMID 35922782, 2022). "The mean and standard deviation (std) of PPARγ mRNA level in tumor and tumor margin groups was 0.21 ± 0.13 and 0.13 ± 0.08, respectively, indicating 1.6-fold increase in PPARγ mRNA level in bone tumors." (PMID 35922782, 2022). "The PPARγ mRNA expression level in bone tumor tissue was significantly higher than its expression level in matched noncancerous bone tissues (P < 0.0001)." (PMID 35922782, 2022). "Comparison of malignant bone tumors with benign bone tumors revealed that the PPARγ protein expression in malignant tumors increased than the benign counterparts (P < 0.0001)." (PMID 35922782, 2022). "A significant elevation of PPARγ gene and protein levels of expression was observed in primary bone tumors compared to normal bone tissues in the current study." (PMID 35922782, 2022). "Comparing the malignant and benign bone tumors, showed a significant increase in the PPARγ mRNA level in malignant (0.23 ± 0.13) vs. benign (0.16 ± 0.09) bone tumors (P = 0.0049)." (PMID 35922782, 2022). "PPARγ might be involved in primary bone tumor pathogenesis and determining its molecular mechanism regarding bone cancer pathogenesis is of grave importance." (PMID 35922782, 2022). "However, the role of PPARγ in bone cancer cell growth is intriguing and both pro-tumorigenic and anti-tumorigenic evidence is revealed." (PMID 35922782, 2022). "Moreover, at both PPARγ protein and gene level, malignant bone tumors revealed a higher level of PPARγ expression." (PMID 35922782, 2022). "Our data provide insights into the efficiency of PPARγ gene and protein expression level to discriminate between primary bone tumor and healthy bone tissue; however, the PPARγ relevance to the chemotherapy outcome and response to treatment need to be validated by future studies." (PMID 35922782, 2022). "Also, determining the prognostic value of PPARγ in patients with varying degrees of primary bone tumor severity and investigate PPARγ protein with more detailed is suggested by further evaluations." (PMID 35922782, 2022). "According to the obtained regression model, expression of PPARγ protein expression in tumor site can be effective in predicting malignancy of bone tumors (OR = 1.59, CI = 1.28–1.98, P-value < 0.0001); the OR was not statically significant for PPARγ gene expression and tumor malignancy." (PMID 35922782, 2022). "Consistently, the protein expression of PPARγ in the tumor site was significantly higher in the bone tumors and malignant tumors compared to non-cancerous and benign tumors, respectively." (PMID 35922782, 2022). "The expression pattern of PPARγ was investigated in the 180 bone tissues including 90 bone tumor tissues and 90 non-cancerous bone tissues." (PMID 35922782, 2022).
bone cancer (continued). "Based on data, the locally expression of PPARγ protein is increased in bone tumor tissues compared to non-cancerous tumor margins (P < 0.0001)." (PMID 35922782, 2022).
Brain atrophy (2 papers, 2014 to 2015). Partial or complete wasting (loss) of brain tissue that was once present. "Here we report that adjunctive therapy with the PPARγ agonist rosiglitazone was associated with enhanced survival, and complete protection from neurocognitive impairment and acute brain injury and subsequent brain atrophy in mice infected with PbA." (PMID 24603727, 2014). "We demonstrate that PPARγ agonists, when administered with anti-malarials, protected mice from developing brain atrophy and neurocognitive impairment." (PMID 24603727, 2014). "Two months following infection, mice that were treated with anti-malarials alone demonstrated cognitive dysfunction, while mice that received PPARγ adjunctive therapy were completely protected from neurocognitive impairment and from PbA-infection induced brain atrophy." (PMID 24603727, 2014).
brain inflammation (2 papers, 2017 to 2025). "In a model of HIV-1-associated brain inflammation, treatment with peroxisome proliferator-activated receptor gamma (PPAR-γ) agonists such as pioglitazone and rosiglitazone induced a neuroprotective M2 phenotype in microglia and reduced neuronal cell death." (PMID 41221080, 2025). "Together our data suggest that targeting PPARγ signaling may provide an option for preventing/treating HIV-associated brain inflammation." (PMID 28886715, 2017). "The goal of this study was to examine the role of PPARγ in the context of HIV-1ADA gp120-induced inflammation in vitro, in primary cultures of rat astrocytes and microglia, and in vivo, in a rodent model of HIV-1ADA gp120-associated brain inflammation." (PMID 28886715, 2017).